MYCN (MYCN proto-oncogene, bHLH transcription factor)
Diseases named in the same sentence as MYCN in open-access papers (continued):
Sharing a sentence is not in itself a finding about the gene and the disease.
neuroblastoma (continued). "Taken together, our study provided convincing data supporting the concept that combining BET bromodomain inhibition JQ1 with immune checkpoint blockade based on PD-1 offers a promising therapeutic approach for high-risk neuroblastoma displaying MYCN amplification." (PMID 36139358, 2022). "Half of high-risk neuroblastoma patients have MYCN amplification." (PMID 35764645, 2022). "Nine of 11 PDX models were MYCN amplified, which is a hallmark of high-risk neuroblastoma." (PMID 36396952, 2022). "Neuroblastoma patients are classified into low-, intermediate-, and high-risk groups based upon the age at diagnosis, tumor histopathology and differentiation, DNA index (ploidy), 11q deletion, and MYCN amplification status." (PMID 36077650, 2022). "However, iron is increasingly linked to neuroblastoma, because there is an elevated requirement for iron in the disease, and because there is an emerging link between MYCN and ferroptosis- a type of cell death mediated by iron." (PMID 36267982, 2022). "In 2009, the International Neuroblastoma Risk Group identified 13 prognostic factors of neuroblastoma through a large-scale cohort study, including age at diagnosis, tumour stage, histological type, degree of differentiation and MYCN amplification." (PMID 35655142, 2022). "MYCN amplification mediated the reprogramming of metabolism is another hallmark of neuroblastoma." (PMID 35764946, 2022). "MYCN amplification is associated with the development of neuroblastoma." (PMID 36171902, 2022). "Thus, a high PHGDH expression is associated with two important neuroblastoma subgroups: those with MYCN amplification and those with 11q LOH and poor prognosis." (PMID 36319669, 2022). "The growth-inhibitory effect of verlindamycin may be caused by polyamine depletion per se and/or by downregulation of MYCN, an oncoprotein, which is the primary driver of proliferation in the high-risk neuroblastoma subset." (PMID 34522028, 2022). "MYCN, a highly amplified oncogene encoding for transcription-factor Kelly cells and a known driver of neuroblastoma progression, was also amongst the most abundant transcripts with a normalized expression of 14.6 (log-normalized: 2.68), placing it as the 106th most expressed gene in Kelly cells." (PMID 36553506, 2022). "Similarly, the increased expression of CIP2A and MYCN has been associated with a worse prognosis in neuroblastoma, making these compounds exciting therapeutics for a patient population in need of novel therapies." (PMID 35454859, 2022). "Amplification of MYCN is the important driver of high-risk neuroblastoma." (PMID 36187481, 2022). "In a zebrafish neuroblastoma model, the additional transgenic expression of the AlkF1174L activated variant overcomes excessive apoptosis observed in MYCN-only tumors, decreasing cell death and promoting tumorigenesis, suggesting an important role for Alk signaling in promotion of survival." (PMID 35972154, 2022). "Further research on MYCN expression and pyroptosis signature may unravel new treatment options for high-risk neuroblastoma." (PMID 35664308, 2022). "In conclusion, our findings suggest that MYCN-amplified high-risk neuroblastoma may be particularly sensitive to the selective loss of RBM39 and modulation of splicing and metabolism by indisulam." (PMID 35296644, 2022). "Like MYCN amplification, 11qLOH can be used as a prognostic marker for NB, and it has been included as an independent risk factor in the pre-treatment risk classification of the International Neuroblastoma Risk Group (INRG)." (PMID 35757140, 2022). "Interestingly, there is a high correlation between T cells, NK cells, and DC infiltration in neuroblastoma tumors, suggesting a coordinated recruitment of these cells, which is associated with a favorable prognosis, independently on MYCN-amplification status." (PMID 36923280, 2022).
neuroblastoma (continued). "In addition, there were low levels of many of the commonly occurring abnormalities in neuroblastoma that were predominantly associated with Clusters 2–4, including MYCN amplification (16%), infant diagnosis (19%) and 11q deletion (19%)." (PMID 36175618, 2022). "The amplification of MYCN gene is the most frequent genomic alteration in neuroblastoma, in association with poor cell differentiation and bad prognosis, which occurs in about 25% of primary neuroblastoma tumors and constitutes the major hallmark of high-risk neuroblastoma." (PMID 34957126, 2021). "A second gene, MYCN, is directly linked to poor prognosis in neuroblastoma patients." (PMID 34769149, 2021). "Thus, a clinical trial of indisulam for high-risk neuroblastoma is warranted, and preclinical studies are needed to evaluate indisulam in other solid tumors such as ovarian cancers with high MYCN levels." (PMID 34788094, 2021). "Thus, CX-5461 is of particular interest in the high-risk subgroup of neuroblastoma, where MYCN amplification is the primary driver and patient outcomes are extremely poor." (PMID 34753908, 2021). "Roughly half of all high-risk neuroblastoma patients present with MYCN amplification." (PMID 34638267, 2021). "Notably, several of these miRNAs were down-regulated in neuroblastoma samples harboring MYCN amplification, which was associated with unfavorable outcome." (PMID 33718173, 2021). "Thus, there is strong evidence that patients with MYCN-amplified neuroblastoma who are otherwise at low or intermediate risk have an inferior prognosis compared to those without MNA." (PMID 34503173, 2021). "Thus, we provide mechanisms that account for the beneficial effects of retinoids in high-risk neuroblastoma and explain the rapid down-regulation of expression of MYCN despite massive levels of amplification of this gene." (PMID 34669465, 2021). "In relation to our research, the presence of CAIX has also been detected in neuroblastoma and its level of expression is associated with a high proliferation rate, chromosomal deletion 1p, and amplification of oncogene MYCN, as well as predicting a poorer prognosis of HR-NB." (PMID 34201814, 2021). "Our earlier work in MYCN amplified neuroblastomas following MondoA or MLX knockdown linked growth arrest and apoptosis with attenuated lipid biosynthesis that could be rescued by OA." (PMID 34669700, 2021). "Thus, exploiting the broad vulnerability of neuroblastoma cells to epigenetic targeting compounds represents an exciting strategy in neuroblastoma treatment, particularly for high-risk MYCN-amplified tumours." (PMID 33968920, 2021). "MYCN amplification was also associated with the clinical outcomes of pediatric neuroblastoma." (PMID 34116676, 2021). "Nevertheless, our findings suggest that rigosertib may add benefit as part of a combination treatment for MYCN-amplified high-risk neuroblastomas." (PMID 34118691, 2021). "A prognostic nomogram using risk score, International Neuroblastoma Staging System stage, age, and MYCN status was built subsequently, and the area under curves, net reclassification improvement, and integrated discrimination improvement showed more satisfactory prognostic predicting performance." (PMID 34746127, 2021). "Furthermore, these cell lines express different combinations of oncogenes known to be important for neuroblastoma development and progression, such as amplified MYCN and mutated or amplified ALK." (PMID 33889818, 2021). "To date, ALK mutations and MYCN amplification are the only validated de novo drivers of neuroblastoma, although a number of other commonly over-expressed proteins and low frequency somatic mutations have been implicated in tumour progression and drug resistance." (PMID 34064704, 2021).
neuroblastoma (continued). "MYCN is a genetic biomarker of high risk and poor outcome in neuroblastoma." (PMID 34113622, 2021). "It has been reported that MYCN gain correlates with anaplasia and reduced relapse-free and overall survival in WT, but it is also associated with poor outcome in other pediatric cancers such as medulloblastoma, neuroblastoma and rhabdomyosarcoma." (PMID 34689785, 2021). "Interestingly, inhibition of STAT3 leads to decreased growth and viability of neuroblastoma cell lines, in addition to decreased levels of MYCN in neuroblastoma cell lines carrying ALK mutations." (PMID 34769149, 2021). "In addition to neuroblastomas, high expression of MYCN or NCYM is associated with poor outcomes in hepatocellular carcinomas or cholangiocarcinomas, respectively." (PMID 34497756, 2021). "Phosphoglycerate dehydrogenase (PHGDH) is a suitable marker for risk stratification, as it is highly upregulated in high-risk MYCN-amplified neuroblastoma; however, its inhibition by small molecule inhibitors antagonized chemotherapy efficiency in patient-derived xenografts in mice." (PMID 35008547, 2021). "With detection of a MYCN amplification in 9 out of 20 neuroblastomas and the detection of 1p36 loss in 8 out of 20 neuroblastomas, results obtained with the NB-HCPS assay were in concordance with the results obtained by the reference laboratory, except for one case." (PMID 34442335, 2021). "MYCN amplification (MNA) is a well-known poor prognostic risk factor in neuroblastoma." (PMID 34893606, 2021). "Here, we found that the expression of ZRF1 mRNA is increased in advanced disease stages and in tumors, with the most common genetic alterations associated with poor prognosis in neuroblastoma, such as MYCN amplification, gain of chromosome 17q, and loss of 1p36." (PMID 34638328, 2021). "We investigated the MYCN-related epigenetic signalling network, and the potential of epigenetic lead compounds as therapeutic agents for the treatment of high-risk MYCN amplified neuroblastoma." (PMID 33968920, 2021). "It has been reported that a PARP inhibitor could enhance DNA replication stress and cause mitotic catastrophe in MYCN dependent neuroblastoma." (PMID 34639028, 2021). "In addition, high expression of PTPN11 mRNA associates with poorer survival of high-risk neuroblastoma patients with MYCN amplification." (PMID 34957126, 2021). "Half of high-risk neuroblastomas harbor MYCN amplification, and the other half overexpress C-MYC." (PMID 34788094, 2021). "MYCN amplification is tightly associated with the poor prognosis of pediatric neuroblastoma (NB)." (PMID 34011924, 2021). "MYCN-amplified neuroblastomas are always considered as high risk." (PMID 33659885, 2021). "Pediatric neuroblastoma patients with MYCN amplification are associated with poor prognosis." (PMID 34116676, 2021). "Furthermore activation of AKT by phosphorylation is associated with poor prognosis in primary neuroblastoma and correlates with amplification of the oncogene MycN, a well-known marker of an aggressive phenotype 16." (PMID 33390782, 2021). "In 10.9% of neuroblastoma tumours with MYCN amplification, additional ALK mutations were found." (PMID 34769149, 2021). "MicroRNAs (miRNAs) may play a role, with let‐7a‐2 that maps to 11q shown to directly suppress MYCN mRNA, perhaps explaining, at least in part, the significant anti‐correlation of 11q deletion and MYCN amplification in high‐risk neuroblastoma." (PMID 33314654, 2021). "Neuroblastoma patients with MYCN amplification are associated with poor prognosis." (PMID 32593299, 2020). "MYCN genomic amplification is reported in 40% of high-risk neuroblastomas." (PMID 33381456, 2020).
neuroblastoma (continued). "By exploring the underlying mechanism of neuroblastoma radioresistance properties, our results highlight interplay between c-Myc and MycN expression suggesting compensatory mechanisms in Myc proteins leading to radioresistance in MYCN-amplified cells." (PMID 32483461, 2020). "Similar abnormalities were found in human high-risk neuroblastoma with MYCN amplification." (PMID 33109237, 2020). "Several alleles appear to specifically confer risk of MYCN‐amplified neuroblastoma, indicating that genetic risk variants may be specific to certain molecular subtypes of neuroblastoma." (PMID 32945147, 2020). "We investigated the association between genetic determinants of height and neuroblastoma risk in 1538 neuroblastoma cases, stratified by MYCN‐amplification status, and compared to 3390 European‐ancestry controls using polygenic scores for birth length, childhood height, and adult height." (PMID 32945147, 2020). "Furthermore, we used multivariate cox regression to determine the association of MYCN target genes in neuroblastoma patients in TARGET and GSE85047 datasets." (PMID 32593299, 2020). "Interestingly MYCN opposite strand (MYCNOS), a non-coding RNA surrounding the MYCN promoter implicated in MYCN upregulation in neuroblastoma, was also upregulated in our SCLC samples." (PMID 32224870, 2020). "Furthermore, it should be noted that the 2p24 chromosomal amplicon observed in high-risk neuroblastoma encodes other genes in addition to MYCN, such as the anaplastic lymphoma kinase (ALK)." (PMID 33585251, 2020). "Amplification of MYCN confers increased malignancy and poorer prognosis in high-risk neuroblastoma." (PMID 33569349, 2020). "This indicates that MYCN gene amplification is an early and perhaps initiating event driving the development of a high-risk neuroblastoma subgroup of tumors which is in contrast to most other cancers where gene amplifications are considered to be late events during tumorigenesis." (PMID 33585251, 2020). "Furthermore, RPS19 in ribosome signaling pathway was also associated with MYCN amplification and correlated with the poor prognosis of neuroblastoma." (PMID 32593299, 2020). "To determine whether an elevated level of MYCN is incompatible with ATRX mutation in human neuroblastoma cells in vivo, we performed an in vivo growth competition assay." (PMID 32060267, 2020). "Additionally, the association of high MYCNOS transcript levels with MYCN amplification and expression has been widely reported in neuroblastoma." (PMID 33270844, 2020). "ROCK may be a promising target for the treatment of high-risk neuroblastoma patients expressing high MYCN levels." (PMID 32244473, 2020). "CYC065 (fadraciclib), a clinical inhibitor of CDK9 and CDK2 (a major regulator of apoptotic cell death), selectively targets MYCN-amplified neuroblastoma through a loss of MYCN transcription and growth arrest, followed by sensitizing cells for apoptosis as a result of CDK2 inhibition." (PMID 33614505, 2020). "However, in neuroblastomas, MYCN amplification and ATRX mutations are mutually exclusive and incompatible." (PMID 32060267, 2020). "Thus, individual genetic variants that influence stature appeared to contribute only modest risk of neuroblastoma or of the MYCN‐amplified subtype of neuroblastoma." (PMID 32945147, 2020). "We evaluated the efficacy of olaparib in the TH-MYCN transgenic mouse model, which leads to high MYCN expression specifically in neural crest lineage cells, and is a widely used genetic model of high-risk neuroblastoma." (PMID 32577161, 2020). "Furthermore, a previous study revealed that CDK4 and MDM2 mutations occurred in melanomas and liposarcoma, while ERBB2 mutations occurred in breast cancer, EGFR mutations occurred in astrocytoma, and MYCN mutations occurred in neuroblastoma." (PMID 32711494, 2020).
neuroblastoma (continued). "High-risk (HR) neuroblastoma is characterized by V-myc avian myelocytomatosis viral oncogene neuroblastoma derived homolog (MYCN) amplification and segmental DNA copy number aberrations which are strongly correlated with poor prognosis, metastasis, and even treatment failure." (PMID 31624245, 2019). "The MYCN amplification is a defining hallmark of high-risk neuroblastoma." (PMID 31856871, 2019). "GWAS (genome-wide associated studies) have shown other genetic variants that are associated with tumor phenotypes, but malignant neuroblastoma has consistently been shown to have high amplification of the MYCN oncogene derived from the short arm of chromosome 2 (2p24)." (PMID 31920530, 2019). "Genetic alterations have been identified in neuroblastomas, including segmental chromosome 1p, 3p, 4p, and 11q deletions, and 1q and 17q gain; gene mutations including MYCN amplification, ALK amplification and mutation, and LIN28B amplification and polymorphism." (PMID 31489113, 2019). "In addition to MYCN gene abnormalities, deletion of 11q was also associated with prognosis in patients with neuroblastoma." (PMID 31338261, 2019). "Notably, the TEAD4-MYCN positive feedback loop was identified to drive high-risk neuroblastoma associated with MYCN amplification." (PMID 31212916, 2019). "MYCN amplification is often associated with a variety of tumors, mostly neuroblastoma." (PMID 31396265, 2019). "Although many molecular prognostic factors have been described in neuroblastoma only activating ALK mutations and MYCN overexpression have been proven to be de novo oncogenic drivers as mutation or overexpression of these molecules give rise to neuroblastoma in genetically engineered mouse models." (PMID 30760980, 2019). "Amplification of MYCN is associated with tumor initiation and progression, and occurs in ~20% of all neuroblastoma cases, with a higher incidence in INSS stages 3 and 4 compared to stages 1, 2, and 4S, suggesting a contribution in regulating oncogenic pathways." (PMID 31624245, 2019). "Moreover, studies had shown that MYCN amplification in serum of patients with neuroblastoma was also associated with overall patient survival." (PMID 31338261, 2019). "In neuroblastoma, genome amplification of the MYCN gene encoding N-myc proto-oncogene protein (N-Myc) and segmental chromosomal alterations, including 1p heterozygous deletions, 11q heterozygous deletions, and 17q increases, are associated with tumor progression and poor prognosis." (PMID 31737108, 2019). "Indeed, these samples represented isogenic cell lines showing the same genetic alterations, including 1p loss, 17q gain and MYCN amplification, which are emblematic of neuroblastoma, and differed only by their ALK status." (PMID 31452835, 2019). "Additionally, as technology and our understanding of the underlying biology of neuroblastoma improve, genomic features beyond MYCN amplification, ploidy, and segmental chromosome aberrations will likely be incorporated in risk classification." (PMID 30754710, 2019). "Amplification of MYCN is the best characterized marker of high risk in neuroblastoma." (PMID 30609639, 2019). "For example, transcription factors of the MYC family (c-MYC and MYCN), which are associated with aggressive pediatric cancers such as medulloblastoma and neuroblastoma, bind to and activate the TERT promoter, resulting in high TERT mRNA levels of MYC- and MYCN-amplified tumors." (PMID 31757062, 2019). "Although the role of Hh-related autophagy seems to be confused currently, encouraging results from MYCN-amplified neuroblastoma and BCR-ABL mutation CML studies underscored the possibility of co-modulating Hh signaling and autophagy to overcome drug resistance in different cancer domains." (PMID 30081498, 2018).